TIMP1 (TIMP metallopeptidase inhibitor 1)
Diseases named in the same sentence as TIMP1 in open-access papers (continued):
Sharing a sentence is not in itself a finding about the gene and the disease.
tumor (continued). "Tissue inhibitor of metalloproteinases-1 (TIMP-1) is a pleiotropic protein, promoting both tumor-suppressive and tumor-promoting activities." (PMID 32034211, 2020). "Telmisartan, an ARB, induces apoptosis of CC cells by reducing cell cycle-related proteins (G1 cyclin, cyclin D1, CDK4, and CDK6), which induces cell-cycle arrest and suppressing tumor growth of CC cells in vivo by inhibiting activation of EGFR and TIMP-1." (PMID 32708604, 2020). "Circulating tumor cells (CTCs) were detected using CellSearch; other biomarkers (EGFR, VEGF, HER2, RAS p21, TIMP1, CAIX) by ELISA." (PMID 30783124, 2019). "In the author’s own research, based on the changes in the expression of tissue inhibitors of metalloproteinases in the whole studied group, a higher expression of TIMP-1 and TIMP-2 was observed in tumor tissues, compared to that in the stroma." (PMID 31223594, 2019). "TIMP-1 and TIMP-2 can block MMP effects in promoting tumor cell proliferation and migration and can also inhibit angiogenesis and apoptosis." (PMID 31886121, 2019). "In the case of the analysis of TIMP-1 and TIMP -2 expressions, in both cases, a higher expression of inhibitors in tumor and stroma was noticed in patients who survived in 3 and 5 years; however, no statistical significance was observed." (PMID 31223594, 2019). "In other studies, plasma levels of LCN2/matrix metallopeptidase 9 complex, MMP2, TIMP1, TIMP2 and TIMP3 were correlated to tumor size, lymph node involvement, tumor differentiation and prediction of tumor stage and T status in patients affected with HNSCC." (PMID 31014274, 2019). "The tumor-related proteins TGF-β1, TIMP1, and MMP9 are partially suppressed by reversine but with different sensitivity in the three cell lines." (PMID 31244554, 2019). "In the present study, no statistical significance was observed regarding the expression of TIMP-1 and TIMP-2 in tumor and stroma depending on the T stage." (PMID 31223594, 2019). "We report that TIMP-1 acts as a double-edged sword in the EOC microenvironment, directly affecting the response to PT treatment on tumor cells and indirectly altering migration and proliferation of endothelial cells." (PMID 31861382, 2019). "Some proteins, such as metalloproteinase inhibitor 1 (TIMP1), 78 kDa glucose‐regulated protein (GRP78), nucleobindin‐2 (NUCB2), and calbindin (CALB1), were found to be significantly changed in only the tumor‐rejecting rats." (PMID 31090175, 2019). "TIMP1, a natural inhibitor of matrix metalloproteinase (MMP) enzymes, inhibits in vitro and in vivo tumor cell invasion and binds several members of the metalloproteinase family." (PMID 31861636, 2019). "This ability was further confirmed by the strong positive correlation between tumour angiogenesis, as demonstrated by VEGF levels, and ECM production and tumour cell invasion tendency, as demonstrated by the MMP-2:TIMP-1 ratio." (PMID 31836811, 2019). "In the assessment of nodal staging from N0 to N3, the expression of TIMP-1 and TIMP-2 was higher in tumor tissues, compared to that in the stroma (P=0.2932, P=0.0085)." (PMID 31223594, 2019). "Regardless of MMPs, their specific tissue inhibitors, including TIMP-1 and TIMP-2, play an important role in tumor progression." (PMID 31223594, 2019). "In comparison with the control group, except for miR-204-5p, the expression levels of ITGA2, FN1, ICAM1, CDH2, TIMP1, CLDN1, TNFRSF12A, miR-146b, and miR-222 were all up-regulated in the tumor group, consistent with the results of the bioinformatics analyses." (PMID 30414611, 2018). "In agreement, immunohistochemical analysis highlighted a strong expression of TIMP1, TSP2, and CCN2 proteins in the tumor stroma." (PMID 29941541, 2018). "A variety of scientific papers have revealed that over-expression of TIMPs, especially TIMP-1 and TIMP-2, can inhibit tumor growth, invasion and metastasis." (PMID 29356905, 2018).
tumor (continued). "We found that all GBM cells expressed the tumor marker GFAP, and some expressed MMP-2 and TIMP-1 both in their cytoplasm and membrane." (PMID 28234925, 2017). "Forward selected, proportional Cox regression of survival modifying parameters (T, N, R, G, tumor localization, MMP2/9, TIMP1/2, CXCR4, and CXCL12) identified CXCR4 being the only survival-modifying parameter in HNSCC." (PMID 29348861, 2017). "As MMP2 and MMP9 facilitates the detachment of tumor cells from primary tumor site and VEGF promotes dissemination via ERK2 and Ras, TIMP1 is directly involved in inhibition of MMP's and halt metastatic process." (PMID 29219852, 2017). "In human colon carcinoma WiDr cells, very interesting results showed that the aberrant glycosylation of TIMP-1 (tissue inhibitor of metalloproteinase-1), through MGAT5 overexpression, increases the malignant behavior and promotes the tumor growth rate." (PMID 26539643, 2016). "The expression level of TIMP1 often correlates with the TNM stage, disease-free survival, the rate of tumor recurrence and even the extent of liver metastasis." (PMID 27644693, 2016). "A cytokine array analysis was also carried out on CM from tumor samples, revealing a strong increase in secretion of the MMP inhibitor TIMP-1, in response to Ab11 treatment and serpinE2 KD." (PMID 27793045, 2016). "Plasma concentrations of VEGF and TIMP-1 were 27% and 49% higher, respectively, in LLC-bearing mice than in non-tumor-bearing mice fed the AIN93G diet." (PMID 27582541, 2016). "To explore the mechanism behind the antitumor activity of grifolin, we performed a screening of genes related to tumor adhesion/invasion regulation, including MMP1,2,3,9,19, TIMP-1,2,3, CD44, CDH1 and PCDH10." (PMID 27626695, 2016). "It inhibits MMP-2, MMP-3, TIMP-1, and TIMP-3 in preventing tumor angiogenesis, and MMP-9 through an autocrine loop in blocking lung and liver metastasis mediated by stromal fibroblasts." (PMID 25909283, 2015). "Next, proteomic assays revealed the presence of ≈150 different proteins, most of which are known tumor supportive factors such as PDGFR-β, TIMP-1, and TIMP-2." (PMID 25669974, 2015). "The 87 HCC patients were divided into two groups: TIMP-1 high expression and TIMP-1 low/non expression using the median ratio of tumor/benign TIMP-1 expression as the cut-off value." (PMID 25909286, 2015). "IHC staining showed higher TR4 level, more macrophage infiltration, lower TIMP-1 and stronger MMP2/MMP9 in tumor tissues of the Gleason score 5 + 4 patients compared with the Gleason score 3 + 3 patients." (PMID 25623427, 2015). "The screening analysis by Proteome Profiler showed distinctly altered expression of sE-cadherin, E-selectin, MMP2, MMP9, TIMP1, TIMP2, Galectin and Clusterin in the serum of tumor patients compared to controls." (PMID 25967040, 2015). "Direct contact between fibroblasts and tumor cells upregulated the secretion and activation of MMP-2, but only NFs increased TIMP-1 production." (PMID 25885552, 2015). "It was previously shown that IL-12 regulates MMP9 and TIMP1 in the tumor micro enviroment leading to reduced MMP9 and increased TIMP1 levels in IL-12 treated tumors." (PMID 27275301, 2015). "TIMP1 was assayed by ELISA in blood samples of 179 CRC patients and 225 neoplasm-free participants and was found to have elevated levels in CRC." (PMID 26253081, 2015). "The study found that in the tumor tissues, MMP-9 and TIMP-1 were significantly higher than in the normal counterparts." (PMID 24520285, 2014). "let-7 family member miRNAs have been shown to be pro-angiogenic and to promote tumour angiogenesis by inhibiting the anti-angiogenic factors thrombospondin-1 (TSP-1) and tissue inhibitor of metalloproteinase-1 (TIMP-1)." (PMID 24886719, 2014). "Multiple stepwise linear regression identified SSTR2, TIMP1 and KCNIP3 as predictors of the response to the acute SA test and SA treatment and RORC as a predictor of tumor size." (PMID 23825587, 2013).
tumor (continued). "That is, increased TIMP1 expression has been correlated with shorter overall survival of GBM patients and TIMP-2 concentrations have been reported to be greater at the tumor margin." (PMID 23349962, 2013). "The cytokine array data demonstrating production of numerous stromal-interacting cytokines (e.g. TIMP-1, MIF, uPA, Serpin E1/PAI-1, MMP-9) suggests that the xenografts are interacting with and being altered by components of the tumor microenvironment." (PMID 24204737, 2013). "There were significant correlations between KAP1, TIMP1 and STC2 levels, and TNM tumor stages and distant metastases." (PMID 23548070, 2013). "For the purpose of this study, formalin fixed paraffin embedded tumor tissue from women recruited into the BR9601 clinical trial, which randomized patients to E-CMF versus CMF, were analyzed for TIMP-1 immunoreactivity." (PMID 23570501, 2013). "Matrix metalloproteinase-9 (MMP-9), tissue inhibitor of metalloproteinases type-1 (TIMP-1) and vascular endothelial growth factor (VEGF) are important angiogenic factors that have a higher expression level in tumor tissues." (PMID 24137341, 2013). "TIMPs are secreted proteins, and it has been debated what kind of cells secrete TIMP-1 due to some reports showed TIMP-1 expression in the cancer cells, and some found TIMP-1 expression in the stromal components of the tumor." (PMID 22988515, 2012). "The antiapoptotic effect of TIMP-1 can be regulated in a MMP-dependent, and a MMP-independent way as a consequence of both direct effects on tumor cells and modulation of the tumor microenvironment." (PMID 23202950, 2012). "Here, we present a novel finding that TIMP-1 signaling upregulates MT1-MMP and MMP-2 expression, and potentiates MT1-MMP activation of pro-MMP-2, contributing to tumor cell invasion." (PMID 22701711, 2012). "Tumor invasion is regulated by numerous NF-κB target gene products, including MMP-9, TIMP-1/2, PAL 2, CXCR4, interleukin-8 (IL-8), and other chemokines." (PMID 22776619, 2012). "CFD/Adipsin median levels were found to be lower in tumours compared to the levels in PN and AN (p = 0.0324), while CXCL5/ENA78, CCL20/MIP-3α, IGFBP3, SPP1/OPN and TIMP1 were increased in PN and tumours relative to AN, with higher levels seen in tumours." (PMID 21092330, 2010). "In the current study, we revealed that the PCs can also control the activity of MMP-2 by acting on the expression levels of MMP-2 inhibitors TIMP-1 and TIMP-2 and the levels of uPAR and PAI-1 in tumor cells." (PMID 20404912, 2010). "TIMP-1 and TIMP-2 gene expression levels were significantly lower in tumors than in adjacent non-tumor tissue samples (p = 0.0169 and p = 0.0127, respectively)." (PMID 19144199, 2009). "The expression of MMP-9 or TIMP-2 by tumour cells, MMP-1, 7, 9, 11, 13, or TIMP-3 by fibroblastic cells, and MMP-7, 9, 11, 13, 14, TIMP-1, or TIMP-2 by mononuclear inflammatory cells, was also significantly associated with a higher rate of distant metastases." (PMID 17342087, 2007). "We found TIMP-1, TIMP-2 and TIMP-3 to be highly expressed both in normal tissue and in tumour tissue, with increased expression in high-grade tumours." (PMID 16465195, 2006). "MMP2 and TIMP2 were the major secretory proteins found in A549 tumour-conditioned medium, whereas MMP9 and TIMP1 were the key proteinases secreted by MDA-MB-231 cells." (PMID 16495926, 2006). "In the present study, TIMP-1 expression was significantly increased in markedly invasive tumors, suggesting that TIMP-1 also plays a role in regulating tumor invasiveness." (PMID 15291964, 2004). "During IL-12 therapy, tumour levels of the matrix metalloprotease MMP-9 declined and its inhibitor TIMP-1 was strongly induced." (PMID 11076665, 2000). "In situ hybridisation showed TIMP-1 and TIMP-2 transcripts predominantly over tumour stroma and gelatinases evenly distributed over both stromal and tumour cells." (PMID 1457364, 1992).
tumor (continued). "Tumor tissues from the sh‐SOX9+vector group displayed a significant reduction in Ki67‐positive cells and an increase in TUNEL‐positive cells, whereas the sh‐SOX9+TIMP1 group showed the opposite pattern." (PMID 41270217, 2026). "Importantly, tumor cell survival and proliferation-promoting activity via CD63 were dependent on TIMP-1 glycosylation, which required N30-glycosylation." (PMID 40345589, 2025). "As shown in, mice receiving anti-Ly6G still exhibited significantly increased liver fluorescence intensity upon TIMP1 overexpression in both tumor models, suggesting that neutrophils are not essential mediators of TIMP1’s metastatic function." (PMID 41511313, 2025). "Our findings explain a previous study demonstrating that only double-glycosylated TIMP-1 but not nonglycosylated TIMP-1 was able to increase tumor growth in vivo." (PMID 40345589, 2025). "The current study is a continuation of our previous research, which focused on the role of other proteases such as metalloproteinases (MMP-9 and MMP-2) and their tissue inhibitors (TIMP-1 and TIMP-2) as candidates for tumor markers in gastro-intestinal malignancies, including CRC." (PMID 40725774, 2025). "We also analyzed protein factors released in the supernatants of US-treated cancer cells, detecting well-known tumor markers (e.g., CA19-9, CEA, and CA125), as well as proteins as candidate novel biomarkers for the detection of PC, particularly B2M, CRP, TIMP1, and Galectin-3." (PMID 40563629, 2025). "Enteric glial cells had fewer potential crosstalk genes, with top regulatory factors ANXA1, TIMP1, and HLA-A, and target genes such as COL1A1 and COL3A1, which may support tumor structure and growth." (PMID 40145096, 2025). "TIMP1 histoscore in neither tumor nor stromal cells showed statistically significant correlation with serum TIMP1 levels." (PMID 39789100, 2025). "These include well-known tumor markers (e.g., CA19-9, CEA, and CA125), as well as proteins more recently described as potential novel biomarkers for the detection of PC (e.g., Beta-2 microglobulin (B2M), TIMP-1, CRP, Galectin-3, uPA, and VEGF-A)." (PMID 40563629, 2025). "Serum TIMP1 levels positively correlated with markers of systemic inflammation and tumor necrosis percentage but not with TIMP1 expression in tumor tissue." (PMID 39789100, 2025). "Notably, we observed an influence of TIMP1, demonstrating a positive correlation with MMP8, MMP9, and MMP10 in tumor samples." (PMID 38474106, 2024). "MMP3, TIMP1, and TIMP2 play critical roles in tumor invasion." (PMID 38921985, 2024). "The significant decrease in TIMP1 expression in Nw and Ob-TME cancer cells may contribute to tumor progression and elevated production of MMP9, an inducible enzyme that may also play an important role in angiogenesis." (PMID 39072314, 2024). "Further research has found that EA can increase the expression level of tissue inhibitors of metalloproteinases (TIMP-1), downregulate the expression of MMP-9, reduce the MMP-9/TIMP-1 ratio, and protect the integrity of the extracellular matrix (ECM), thereby inhibiting tumor metastasis." (PMID 38803433, 2024). "We further demonstrated that both T cells and DCs secrete TIMP-1 and that its soluble form increased the expression of MHC-I in myeloid DCs, exposed to tumor antigens, highlighting its potential to enhance antigen presentation in DCs, particularly in classical type 1 dendritic cells (cDC1)." (PMID 38777826, 2024). "Increased expression of TIMP1, MMP1, AGRN, UNC5A, and ADAMTS4 was observed, while the expression of UNC5C, TINAG, SPOCK3, and ITGA7 was reduced in the normal FHC cells compared to the HCT8 tumor cells." (PMID 39011483, 2024).
tumor (continued). "Expression analysis showed that MMP3, MMP9, TIMP1 and VEGFA were upregulated in tumor samples." (PMID 39177661, 2024). "The novelty of this study is that there is evidence of a strong association between circulating vesicles derived from adipocytes carrying pro-angiogenic MMPs and not expressing their inhibitor TIMP1 with the level of angiogenesis in the primary tumor." (PMID 37109070, 2023). "Furthermore, blocking TIMP-1 by neutralizing antibodies inhibited the growth of implanted TNBC in mice, suggesting TIMP-1 as an actionable biomarker for this tumor." (PMID 37443843, 2023). "Collectively, our data indicate that TIMP1-FL and TIMP1 Δ4-5 play distinct roles in CRC carcinogenesis and that TIMP1 Δ4-5 may act as a potential tumor suppressor in CRC." (PMID 37735421, 2023). "Moreover, the expressions of TIMP1, PGF, FSTL3, SNAI1, and FOXC1 were significantly up‐regulated in the tumor tissues." (PMID 37017587, 2023). "The current study shows that COL1A2, followed by TIMP-1, are the most potent CAF-markers found and verified at the transcriptome and protein level across multiple CAF types, differentiating CAF from tumour epithelia and normal fibroblast in HNSC patient samples." (PMID 37626157, 2023). "TIMP1 (tissue inhibitor of matrix metalloproteinase 1) was shown to be correlated with cancer progression, specifically in GBM, and is significantly overexpressed in tumor-infiltrating lymphocytes." (PMID 37568715, 2023). "In the independent validation set, we found regulatory chains with GAS6, TIMP1, SPP1, and VEGFA as ligands, which was consistent with our findings above, indicating that these regulatory relations may be ubiquitous in tumor cells and macrophages." (PMID 37189418, 2023). "We also analyzed the correlation of TIMP-1 expression with EFS in treated TPBC (ER+, PR+, HER2 expression) patients of different tumor stages, without finding any significant association with prognosis (p = 0.34)." (PMID 37443843, 2023). "In addition, except for TIMP1 (P > 0.05), the expression levels of INHBA (P < 0.05), LAMC2 (P < 0.05), PLAU (P < 0.05) and TGFβ1 (P < 0.05) were significantly different between tumour and normal samples." (PMID 37325056, 2023). "In another study, polyphenolic-rich ethanolic Spatholobus suberectus stem extract protected against ROS and cellular damage via inhibition of MMPs, upregulation of TIMP1, and the blockade of MAPK phosphorylation following UVB-induced skin photoaging in human epidermal keratinocytes (HaCaT)." (PMID 37351505, 2023). "The gene expression of TIMP1, MMP2 and MMP9 has been assessed in tumor tissue and blood." (PMID 37509417, 2023). "The tumor-regressive effect of JZL184 was accompanied by a dose-dependent reduction in the angiogenesis marker CD31 and a likewise dose-dependent increase in TIMP-1-positive cells in xenografts." (PMID 37443791, 2023). "We also found that atorvastatin can increase the sensitivity of NSCLC cells to carboplatin by inhibiting protein kinase B (Akt) activation and up-regulating Recombinant Tissue Inhibitors of Metalloproteinase 1 (TIMP1) expression, thus increasing the survival time of NSCLC tumor-bearing mice." (PMID 37978381, 2023). "The distribution of cancer cells and stromal cells in tumor spheroids did not change significantly with TIMP‐1 silencing." (PMID 35600659, 2022). "The protein expression of PCOLCE2, APOD and TIMP1 displayed no significant changes in tumor and normal thyroid tissues." (PMID 36387901, 2022). "CMCS-NCTD could also exert anti-metastasis effects by inhibiting tumor angiogenesis and decreasing degradation of extracellular matrix by regulating the levels of VEGF, MMP-9 and TIMP-1 in Lewis lung carcinoma metastasis model." (PMID 36463199, 2022). "The tumor sections with the first antibody anti-TIMP-1 omitted and incubated with PBS (negative control) did not exhibit positive staining." (PMID 36518899, 2022).